EIF4E (eukaryotic translation initiation factor 4E)
Diseases named in the same sentence as EIF4E in open-access papers (continued):
Sharing a sentence is not in itself a finding about the gene and the disease.
cancer (continued). "The eukaryotic translation initiation factor 4E (eIF4E) is a potent oncogene elevated in an estimated 30% of human cancers, and the eIF4E protein provides the critical interface between mRNA, recruitment of eIF4A and eIF4G, and the 40S ribosomal subunits." (PMID 25749979, 2015). "This virus expresses 4EBP-1 and interferes with the oncogenic function of eIF4E, inhibiting the proliferation of cancer cells with promising results." (PMID 25690796, 2015). "Both FGFR3 and eIF4E have been shown to promote tumor growth, and are overexpressed in human cancers including CRC." (PMID 26078354, 2015). "Consistent with this, studies have shown a positive correlation between increased eIF4E phosphorylation and cell proliferation, and highly phosphorylated eIF4E was observed in a variety of cancers." (PMID 25915158, 2015). "An early study described the post-transcriptional regulation of eukaryotic translation initiation factor 4E (eIF4E) (the cap-binding protein), whose levels are highly elevated in many human cancers." (PMID 26404389, 2015). "The discovery that the anti-viral drug ribavirin has eIF4E inhibitory activity has resulted in its re-appropriation as a cancer therapy." (PMID 26501340, 2015). "For instance, it is well known that the altered expression of the translation initiation factor eIF4E contributes to cancer progression by enabling the translation of a limited pool of mRNAs encoding key proteins involved in cellular malignancy." (PMID 25886394, 2015). "eIF4E is indeed frequently over-expressed and over-activated in human cancers, and acts at a converging point of relevant oncogenic pathways." (PMID 26041884, 2015). "EIF4E is also highly expressed in cancer cells and, together with EIF4A, accelerates and maintains T‐cell acute lymphoblastic leukaemia (T‐ALL) in cultured mammalian cells." (PMID 26493293, 2015). "Another example of NPC programming and elevated mRNA export contributing to cancer is provided by eIF4E." (PMID 26343730, 2015). "In summary, because phosphorylation of eIF4E is associated with resistance to cellular stress, with tumor development in mice models, and worse prognosis in human tumors, the use of specific inhibitors of eIF4E phosphorylation may be a promising approach in cancer treatment." (PMID 25923732, 2015). "eIF4E is highly elevated in a wide variety of human cancers suggesting that eIF4E can reprogram the NPC to promote proliferation and survival." (PMID 26343730, 2015). "Despite extensive interest in the eIF4E, eIF4G and eIF4A components, few studies have addressed the function of eIF4A cofactors, namely eIF4H and eIF4B, in cancer progression." (PMID 26498689, 2015). "The levels of eIF4E (a c-Myc target gene) which is involved in cytoplasmic mRNP processing, were significantly reduced in carcinoma cells, as were the levels of Dcp1a, another constituent of P-bodies." (PMID 25669982, 2015). "Overexpression of eIF4E has been found in a range of human cancers and phosphorylation of eIF4E by Mnks is responsible for the oncogenic role of eIF4E." (PMID 25277198, 2014). "Both eukaryotic translation initiation factor 4E (eIF4E) and integrin αvβ6 play an important role in the development and progression of cancer." (PMID 24839543, 2014). "While the other functionally complementary scaffolding factors eIF4E and eIF4GI have been described as significantly increased in a variety of cancers, our studies are the first to implicate eIF4GII in a malignancy." (PMID 24497838, 2014). "Recent studies have suggested that activation of eIF4E is particularly important for the translation of a subset of cancer promoting mRNAs including cyclin D1 and anti-apoptotic proteins." (PMID 24504069, 2014). "The phosphorylation of eIF4E on Ser-209 is frequently increased in cancer cells and eIF4E expression levels are upregulated in many tumors." (PMID 25193863, 2014).
cancer (continued). "It should be noted that targeting the Mnk pathway represents an attractive target for the treatment of these cancers because Mnk activity – while being necessary for eIF4E-mediated oncogenic transformation – is dispensable for normal development." (PMID 25193863, 2014). "Partial loss of large ribosomal subunit protein 24 (RPL24) function is known to protect mice against Akt or Myc-driven cancers, in part via translational inhibition of a subset of cap(eIF4E)-dependently translated mRNAs." (PMID 24970821, 2014). "Mnk mediated eIF4E phosphorylation favors mRNA translation of proteins involved in cell proliferation and survival, and correlates with cancer cell proliferation." (PMID 24504069, 2014). "As an oncogene, eukaryotic translation-initiation factor 4E (eIF4E) is widely overexpressed in various cancers." (PMID 25904822, 2014). "eIF4E overexpression has been noted in many cancer types, and eIF4E overexpression in a mouse model cooperated with Myc to cause B cell transformation." (PMID 24586420, 2014). "In fact, a growing body of evidence suggests that dysregulation of eIF4E and other canonical translation factors such as eIF4A differentially target specific subsets of cancer-promoting mRNAs." (PMID 25392452, 2014). "eIF4E is an oncogene as it is overexpressed in many human cancers with poor prognosis and its overexpression results in transformation of cells in vivo." (PMID 25505994, 2014). "Our results agree with recent findings that the 4EBP/eIF4E ratio is a crucial determinant of asTORi sensitivity in cancer cells, and extend this model to a naturally occurring DLBCL line deficient in 4EBP1." (PMID 24586420, 2014). "It has demonstrated that mice carrying a serine-209Ala eIF4E mutant were incapable of developing cancer." (PMID 25277198, 2014). "The phosphorylation of eIF4E promotes proliferation and survival rate of tumor cell and are critical for malignant transformation and cancer progression." (PMID 24551240, 2014). "Initiation factor eIF4E is now considered to be a bone fide oncogene product, based on data from transgenic mouse studies and the fact that many cancers have enhanced levels and/or activity of the protein." (PMID 23940704, 2013). "Aggressive cancer cells often take advantage of mitogenic signaling pathways to activate mTOR and free up eIF4E to maintain their survival and growth." (PMID 24180592, 2013). "In previous work, the 4EASO was shown to diminish eIF4E levels and induce apoptosis in a panel of human cancer cell lines at nanomolar concentrations." (PMID 24260583, 2013). "Further, suppression of eIF4E levels reduces translation of proteins that perform at the junction of cellular pathways that control essential functions for cancer genesis, progression and metastasis." (PMID 24260583, 2013). "In cancer, eIF4F potency is enhanced either by an increase in eIF4E expression or by cell signaling through PI3K/AKT/mTOR pathway or by both." (PMID 24260583, 2013). "Selective targeting of eIF4E mRNA by specific antisense oligonucleotide (ASO) therapy has also been studied in cancer." (PMID 24260583, 2013). "The success of these investigations led to a phase 1 clinical trial of 4EASO (LY2275796) in human cancer that clearly demonstrated reduction of eIF4E mRNA and protein within patient tumor tissues." (PMID 24260583, 2013). "One of the major mechanisms that cancer cells maintain higher efficiency of translation initiation involves stimulation of translation initiation factor, eIF4E." (PMID 24180592, 2013). "A number of studies demonstrated the role of integrins in translation of survival and growth factors through enhancing eIF4E function, but the exact mechanism by which integrins control translation initiation of cancer related mRNAs remains to be determined." (PMID 24180592, 2013). "These approaches of directly targeting eIF4F integrity and function by eIF4E antagonism provide evidence of therapeutic efficacy in each cancer studied." (PMID 24260583, 2013).
cancer (continued). "Cercosporamide effectively blocked eIF4E phosphorylation at Ser209, suppressing cancer cell proliferation and colonization and leading to induction of apoptosis." (PMID 22392765, 2012). "A role for eIF4E as a prognostic marker has also been suggested for certain cancers and the involvement of eIF4E in metastasis has been considered." (PMID 22392765, 2012). "Overexpression of eIF4E in mammalian cells is an important determinant of cell proliferation which is observed in several cancer forms." (PMID 23226381, 2012). "Given the important role of eIF4E in tumorigenesis, reducing either eIF4E activity or levels in cancer cells has become an attractive anticancer strategy." (PMID 22666083, 2012). "For these reasons, dual targeting of both Akt and mTOR, or directly inhibiting eIF4E activity, have been proposed as treatments for cancer." (PMID 22392765, 2012). "Eukaryotic initiation factor (eIF)4E is over-expressed in many types of cancer such as breast, head and neck, and lung." (PMID 23094039, 2012). "It has been shown that prolonged treatment of cancer cells or patients with mTOR inhibitors causes elevated PI3K activity that leads to phosphorylation of Akt and eIF4E, and promotes cancer cell survival." (PMID 22392765, 2012). "eIF4E, a eukaryotic translation initiation factor, which is elevated in 30% of cancers, binds 7-methyl guanosine cap on mRNA enhancing nuclear RNA transport and translation." (PMID 23164412, 2012). "Amongst the many clients whose activity is modified by HspB1, one can cite the translation initiation factor 4E (eIF4E) which modulates the translational initiation process, a crucial parameter for cancer cell growth and proliferation." (PMID 24278676, 2012). "eIF4E is also known to regulate the expression of such important molecules in cancer development as vascular endothelial growth factor (VEGF), survivin, c-myc." (PMID 23164412, 2012). "Deregulation of protein synthesis is a common event in human cancer and a key player in translational control is eIF4E." (PMID 22392765, 2012). "mTOR signaling is one of the major regulators of translation in cancer cells by altering 4EBP-1 and eIF4E activity." (PMID 23259068, 2012). "Adhesion plays also an important role in cancer metastasis and mammalian eIF4E and eIF4E-BPs have been shown to be involved via the mTOR pathway." (PMID 23226381, 2012). "4E-BP1 is directly phosphorylated by mTORC1, potentially leading to increased eIF4E activity and enhanced translation of cancer-related transcripts." (PMID 21320304, 2011). "In both xenograft nude-mouse and more genetically and clinically relevant mouse cancer models, overexpression of eIF4E was shown to both accelerate the onset of tumor formation and aggravate its drug response." (PMID 21378410, 2011). "Another nucleoside analog, ribavirin, has recently garnered some attention as a novel anti-eIF4E cancer therapeutic." (PMID 21378410, 2011). "c-Myc induction of eIF4E in cancer cells is frequently used as a cellular model to study the molecular mechanism of cancer proliferation, but its interaction with the expression signature of miR-145 is not completely understood." (PMID 21092188, 2010). "Expression of eIF4E is commonly elevated in many human cancers and, frequently, it induces cellular transformation, tumorigenesis and metastasis selectively enhancing the translation of mRNAs of potent growth regulatory proteins such as Cyclin D." (PMID 20462454, 2010). "eIF4E protein positive expression of WD/MD cancer tissue was significantly lower than those in PD/ND cancer tissue." (PMID 21159249, 2010). "The protein EIF4E is a translation initiation factor, and mRNA expression is reported to be elevated in many human cancers." (PMID 20459617, 2010).
cancer (continued). "We conclude that eIF4E's influence on cancer survival is modulated substantially by 4E-BPs, and that combined pathway analyses can estimate functional eIF4E." (PMID 19367274, 2009). "These cancers develop despite the fact that the level of eIF4E overexpression in these mice is much less than the corresponding levels of eIF4E overexpression found in patients." (PMID 20049173, 2009). "We show that eIF4E and 4E-BP expression are positively associated, and that 4E-BP2 has a stronger influence on cancer behaviour than 4E-BP1." (PMID 19367274, 2009). "Enhanced cap-mediated translation in cancer often occurs after either an overexpression of eIF4E, phosphorylation of eIF4E, or an inactivation of the 4E-BP1 repressor protein." (PMID 19603014, 2009). "Mice with transgene overexpression of eIF4E developed a variety of cancers of distinct histological origin." (PMID 20049173, 2009). "There is evidence that cancer cells have developed an oncogene addiction to, or dependency on, eIF4E." (PMID 20049173, 2009). "We discussed the dysregulation of eIF4E in multiple cancers and the current strategies being considered to target its activity." (PMID 20049173, 2009). "Novel agents are being developed for targeting eIF4E or for disabling the eIF4F molecular complex as a potential cancer therapy." (PMID 19603014, 2009). "Increased eukaryotic translation initiation factor 4E (eIF4E) expression occurs in many cancers, and makes fundamental contributions to carcinogenesis by stimulating the expression of cancer-related genes at post-transcriptional levels." (PMID 19367274, 2009). "We have not examined 4E-BP3 because it is not thought to have a role in breast, or phosphorylated forms of eIF4E, as their influences on the activity and in cancer remain uncertain." (PMID 19367274, 2009). "Clinical trials of the efficacy and safety of cancer therapeutics that target eIF4E have been carried out and some toxicity has been reported." (PMID 19367274, 2009). "The eIF4E is frequently overexpressed in human cancers in relation to disease progression and drives cellular transformation [reviewed in 45]." (PMID 18596980, 2008). "Downregulation of eIF4E and its downstream targets is a potential therapeutic option for the development of novel anti-cancer drugs." (PMID 17311107, 2007). "This study identified novel anti-apoptotic eIF4E targets, including survivin, which has a well-documented role in cancer cell growth and cell survival." (PMID 17311107, 2007). "eIF4E protein levels are substantially elevated in many cancers including colon, breast, bladder, lung, prostate, gastrointestinal tract and head and neck cancers; Hodgkin's lymphomas and neuroblastomas." (PMID 17311107, 2007). "Several of the ribosomal proteins identified here as targets of eIF4E are upregulated in different cancers." (PMID 17311107, 2007). "In AML, eIF4E controls the nuclear export and translation of selective mRNA through its specific recognition and binding of the m7G 5′ end cap structure, which in turn leads to cancer progression." (PMID 41208200, 2025). "Cancer cells may develop resistance to eIF4E inhibitors over time, limiting their long-term efficacy." (PMID 40225856, 2025). "In the context of cancer, MNKs are involved in the phosphorylation of eIF4E." (PMID 39779613, 2025). "Thus, B56-PP2A activation is a promising approach for repression of aberrant eIF4E-dependent translation for therapeutic benefit in cancer patients." (PMID 39869680, 2025). "FDA-approved antiviral drug ribavirin has been shown to suppress eIF4E in cancer." (PMID 39779613, 2025). "Recent advancements of in‐depth understanding the aberrant translation control process led to the identification of diverse therapeutic targets for cancer treatment, and among all the eIF4E represents a promising one due to its multiple roles in carcinogenesis and progression." (PMID 40308810, 2025).
cancer (continued). "In addition, eIF4E expression levels are elevated in a variety of cancers, and it can also serve as an important therapeutic target." (PMID 41208200, 2025). "In this regard, the eukaryotic initiation factor 4F complex (eIF4F) composed of eIF4E-eIF4G-eIF4A is located at the convergence of several pathways involved in cancer, notably the PI3K/Akt/mTOR and potentially the oncogenic STAT1 that promotes the expression of B-cell lymphoma xl (Bcl-xL) gene." (PMID 40332401, 2025). "In addition to the wealth of data demonstrating that eIF4E contributes to oncogenic transformation, it is also clear that eIF4E is an essential regulatory hub in cancer signalling networks." (PMID 40016190, 2024). "EIF4E is a prooncogenic molecule overexpressed and involved in many types of cancers." (PMID 38385078, 2024). "Besides, allosteric mTORi can modestly reduce p4E-BP1 levels through the inhibition of (4E-BP1) phosphorylation, and consequently, cannot effectively restrain eIF4E-mediated cap-dependent translation initiation in cancer." (PMID 37596643, 2023). "Notably, ATP-competitive mTORi remarkably reduce p4E-BP1 levels through the inhibition of (4E-BP1) phosphorylation, and as a result, can effectively prevent eIF4E-mediated cap-dependent translation initiation in cancer." (PMID 37596643, 2023). "eIF4E levels are rate-limiting for cancer development, as shown by the fact that in mice, a reduced dosage of eIF4E, while compatible with normal development and global protein synthesis, significantly impeded cellular transformation through its action on specific 5′UTRs." (PMID 36902316, 2023). "Thus, mTORC1 signalling is hyperactivated in many cancers, increasing the availability of eIF4E and promoting translation initiation and the translation of a subset of mRNAs (rather than every mRNA)." (PMID 37143925, 2023). "Moreover, phosphorylated eIF4E (p-eIF4E) is often upregulated in different cancer types, and phosphorylation of eIF4E is involved in essential processes in cancer biology, including cell transformation, proliferation, apoptosis, metastasis, and angiogenesis." (PMID 36994107, 2023). "With the increase of HuR level, the stability of eIF4E mRNA in cancer cells is improved." (PMID 37601696, 2023). "Importantly, mTOR persistently restrains the tumor-suppressive function of 4E-BP1 via phosphorylation thereby releasing 4E‐BPs from eIF4E and enabling cap-dependent translation initiation in cancer." (PMID 37596643, 2023). "This suggests that mammalian cells express eIF4E above the threshold required for normal translational control but that the factor may be upregulated by cancer cells to induce the translation of specific subgroups of oncogenic mRNAs." (PMID 37631029, 2023). "It was reported that eIF4E levels in cancer cells are much higher than in normal development, therefore, partially inhibiting eIF4E may be effective in killing cancer cells without being toxic to normal cells." (PMID 37190120, 2023). "eIF4E is upregulated in a number of human cancers, and eIF4E phosphorylation by MNKs may play an important role in cancer biology." (PMID 36409629, 2023). "Activation of eIF4E was indispensable for the transformation of mouse models of cancer." (PMID 37888706, 2023). "The expression of eIF4E is closely related to a variety of malignant tumors." (PMID 37601696, 2023). "With the progress of cancer, the expression of eIF4E is increasing." (PMID 37601696, 2023). "EIF4E is widely overexpressed in human cancers as an important therapeutic target." (PMID 36274088, 2022). "Studies have shown that knocking down eIF4E can inhibit cancer cell proliferation and angiogenesis." (PMID 36225177, 2022). "For example, EIF4E in the C6 cluster is involved in protein synthesis and a key checkpoint in the control of the rate of mRNA translation, and EIF4E has a critical role in the pathology of various types of cancer." (PMID 36421809, 2022).